KRTAP24-1 (keratin associated protein 24-1)
Description:
In the hair cortex, hair keratin intermediate filaments are embedded in an interfilamentous matrix, consisting of hair keratin-associated proteins (KRTAP), which are essential for the formation of a rigid and resistant hair shaft through their extensive disulfide bond cross-linking with abundant cysteine residues of hair keratins. The matrix proteins include the high-sulfur and high-glycine-tyrosine keratins.
Synonyms: KAP24.1
Tractability: No criterion of Open Targets' tractability assessment is met for any kind of drug.
Gene: Protein-coding gene on chromosome 21 (30,281,309 to 30,282,950, reverse strand). Ensembl gene ENSG00000188694.
Pathways (Reactome):
Developmental Biology: Keratinization
Gene Ontology:
Molecular function: structural molecule activity
Cellular component: cytosol; keratin filament
Genetic constraint (gnomAD): Loss-of-function variants: 0 observed, 1.32 expected, observed/expected ratio (o/e) 0, 90% interval 0 to 1.62. That is too few expected variants to judge how well the gene tolerates losing a copy. Missense variants: 344 observed, 315.81 expected, observed/expected ratio (o/e) 1.09, 90% interval 1 to 1.19. Synonymous variants: 133 observed, 122.37 expected, observed/expected ratio (o/e) 1.09, 90% interval 0.94 to 1.25.
Homologues: Orthologues: chimpanzee KRTAP24-1 (96% identical), macaque KRTAP24-1 (89% identical), dog KRTAP24-1 (68% identical), pig KRTAP24-1 (67% identical), rabbit KRTAP24-1 (63% identical), mouse Krtap24-1 (59% identical), rat Krtap24-1 (57% identical). Paralogues in human: KRTAP3-3 (15% identical), KRTAP3-2 (14% identical), KRTAP3-1 (14% identical).
Diseases named in the same sentence as KRTAP24-1 in open-access papers:
KRTAP24-1 is named in the same sentence as 1 disease in open-access papers, as found by Europe PMC text mining. Sharing a sentence is not in itself a finding about the gene and the disease. The quoted sentences say what the papers report.
cancer (1 paper, 2022). A tumor composed of atypical neoplastic, often pleomorphic cells that invade other tissues. "Genes such FAM182A, SOX9, AHNAK2, ENSG00000121031, FLT3LG, PMEPA1, ZFP36L2 in the large intestine, ALB, KRTAP19-1, APOB, CD200, CRYGD, KRTAP24-1, OR6N2 in the liver are novel predictions, and their functions in these cancers can further be studied." (PMID 34997044, 2022).